CXCL8 (C-X-C motif chemokine ligand 8)
Diseases named in the same sentence as CXCL8 in open-access papers (continued):
Sharing a sentence is not in itself a finding about the gene and the disease.
cancer (continued). "Finally, by analyzing transcriptomic databases for a wide array of human cancer cell lines representing different types of solid tumors, including breast, we uncovered significant correlations between CXCL8 and a number of TGF-β1/TNF-α–associated genes." (PMID 40833805, 2025). "In this study, we report that in HNSCC, CXCL8 expression is activated via NF-κB/p65 protein phosphorylation at the Ser536 site by ROS induced under conditions of glucose deficiency, whereas CXCL8 increases CLU expression in TAMs to facilitate antioxidative stress in cancer cells." (PMID 39905539, 2025). "Current study suggested that the CXCL8 -353 and +781 polymorphisms may be associated with a greater risk of cancer, which might impact cancer prevention, diagnosis, or treatment through the different expression of CXCL8." (PMID 38807156, 2024). "We surmised that -353 or +781 polymorphism may increase the expression of CXCL8, as a similar oncogene, which can result in the increased incidence of cancer." (PMID 38807156, 2024). "Above articles indicated SNPs from CXCL8 may be associated with the different expression of CXCL8 and status of inflammation and oxidative stress, then result in the development of cancer and be considered as a druggable protein for treatment of cancer." (PMID 38807156, 2024). "CXCL8, a proinflammatory chemokine and a chemoattractant for myeloid leukocytes, is generally considered to be a protumorigenic factor and is associated with poor prognosis in cancer patients." (PMID 37898619, 2023). "Two studies conducted in CRC and pancreatic ductal adenocarcinoma indicated that mesenchymal stem cells (MSCs) and cancer-associated fibroblasts (CAFs) could promote cancer cells secreting CXCL8, then enhancing the ability of proliferation and invasion." (PMID 35372515, 2022). "Additionally, CXCL8 also enhances cancers by controlling stem cell mass, and CXCL1 is associated with the occurrence of drug resistance." (PMID 36431173, 2022). "In addition, in various cancers, high release of CXCL8 was associated with the poor effects of drugs (e.g., oxaliplatin, 5-fluorouracil, paclitaxel, and camptothecin)." (PMID 36612163, 2022). "For example, evidence from our studies indicated that co-culturing of TNBC cells with mesenchymal stromal cells (MSCs) or cancer-associated fibroblasts (CAFs) in the presence of TNFα or IL-1β stimulation has given rise to contact-dependent increase in CXCL8, CCL2 and CCL5 levels in the co-cultures." (PMID 32605277, 2020). "In addition to these important roles of cancer cell-derived chemokines in cancer progression, our study demonstrated that CXCL8 in CAFs was closely associated with GC progression and worse prognosis of GC patients." (PMID 31147602, 2019). "In addition to its physiological roles in neutrophil chemotaxis, CXCL8 has been implicated in many of the pathological processes involved in cancer progression." (PMID 24276377, 2013). "Lastly, the specific polymorphic sites within the CXCL8 gene can have varied functional effects, leading to distinct changes in CXCL8 expression that may ultimately translate to shifts in the risk of developing cancer." (PMID 38807156, 2024). "The hyper-activation of Cxcl8 could be associated with cancer promotion." (PMID 33585006, 2020). "Also, the cytokine array analysis revealed that the mechanism may be associated with CXCL8 derived from TAMs binding to CXCR1/2 secreted by PTC cells to promote cancer cell metastasis." (PMID 32626535, 2020). "Increasing evidence underscores the significant role of the CXCL8–CXCR1/2 axis in the TME, along with the predictive significance of serum CXCL8 levels in human cancers following immune checkpoint blockade therapy." (PMID 41503514, 2026). "CXCR1/2, a G-protein coupled rhodopsin-like seven transmembrane domain receptors, is mainly expressed on neutrophils, macrophages, as well as cancer cells, and is indispensable for CXCL8-mediated signaling activation and biological function." (PMID 39897048, 2025).
cancer (continued). "In line with our previous findings, we found homogenous upregulation of CXCL8 after irradiation across the investigated cancer cell lines, which correlated with increased chemotaxis of NK cells." (PMID 40811032, 2025). "The second, F6: inflammatory myofibroblasts (IL11+MMP1+CXCL8+IL7R+), characterizes early human skin wounds, inflammatory diseases with scarring risk and cancer." (PMID 40993240, 2025). "Moreover, colocalization statistics revealed that GDUGS-defined glucose deficiency, CXCL8 expression and macrophage distribution were significantly correlated, suggesting that cancer cell-derived IL-8 may induce CLU expression in TAMs to facilitate antioxidation in various types of cancer." (PMID 39905539, 2025). "Differential analysis between high-risk and low-risk cancer cells revealed that high-risk cancer cells exhibited elevated expression of genes associated with M2 macrophages, including CXCL2, IL6R, CXCL8, GDF15, CD68, and PTX3." (PMID 41034991, 2025). "Immune checkpoint inhibition (ICI) has emerged as a cornerstone of immunotherapy for various cancers, and recent trials underscore the critical role of CXCL8 in the efficacy of ICI treatments." (PMID 40006729, 2025). "Next, we analyzed the correlation between serum CXCL8 and ROS levels of cancer tissues, and found a significantly positive correlation between their levels." (PMID 39660100, 2025). "SYTL4 mediates CXCL8 secretion from gemcitabine-resistant cancer cells; therefore, we further examined its role in fibroblast–glutamine exchange." (PMID 41444422, 2025). "CXCR2, a receptor for chemokines like CXCL5 (ENA-78) and CXCL8 (IL-8), is involved in various aspects of cancer biology." (PMID 41149503, 2025). "Ex vivo, inflammatory molecules released from cancer cells [e.g., IL‐8/CXCL8, granulocyte colony‐stimulating factor (G‐CSF), CXCL1, CXCL2, Cathepsin C, and Toll‐like receptor (TLR) ligands] can induce NETs." (PMID 39865544, 2025). "We found that TGF-β–related genes show high fold-enrichment within the top 100 CXCL8-correlated genes across all cancer cell lines." (PMID 40833805, 2025). "CXCR1 serves as a receptor for interleukin-8 (IL-8, also known as C-X-C motif chemokine ligand 8), a central mediator of immune and inflammatory responses involved in many disorders including cancer." (PMID 40109299, 2025). "NETs stimulated the stimulator of interferon genes (STING) pathway of cancer cells to produce interleukin-8 (IL-8, also known as CXCL8), which would recruit more neutrophils." (PMID 40046958, 2025). "A positive correlation was recognized between SLC2A1 expression and chemokines in numerous cancer types, with CCL7/26 and CXCL8 being primarily associated with LUAD." (PMID 40824962, 2025). "The chemokine CXCL8 is a well-established mediator of inflammation, angiogenesis, and immune evasion in cancer." (PMID 40087784, 2025). "CXCL8, which contributes to the progression of several types of human cancer progression 34, was also significantly higher in patients with excellent CRT response in our study." (PMID 40092701, 2025). "Despite these challenges, research has shown that NET formation induced by stimuli such as LPS and IL-8/CXCL8 is heightened in gastric and colorectal cancer." (PMID 40801632, 2025). "Cancer cells expressed multiple SASP-associated CC (e.g., CCL20) and CXC (e.g., CXCL1, CXCL8, CXCL16) chemokines, which have been shown to be induced by radiotherapy in preclinical models." (PMID 40811032, 2025). "While CXCL8’s involvement in cancer progression and drug resistance has been extensively studied, its role in radiotherapy resistance in CC remains unexplored." (PMID 40596054, 2025). "Recent studies have also shown that CXCL8 can modulate the immune microenvironment, influencing the efficacy of immune checkpoint inhibitors in cancer treatment." (PMID 39962077, 2025). "The top five upregulated genes (MMP1, COL10A1, CXCL8, TM4SF1 and PLAU) have been associated with cancer progression and metastasis-inducing mechanisms." (PMID 40640495, 2025).
cancer (continued). "We searched for other potential overlaps and found that CXCL2, LIF, UBE2C, KRT5, ICAM1, and CXCL8 were significantly upregulated in STIC lesions identified in patients with cancer compared with adjacent normal epithelium." (PMID 40689422, 2025). "The immunotherapeutic potential of the CXCL8-chemokine/CXCR2-chemokine-receptor system is currently being explored in numerous human cancers." (PMID 38900374, 2025). "Changes in the CXCL8 signaling pathway inhibited cellular apoptosis and promoted multidrug resistance, thereby reducing the sensitivity of cancer cells to chemotherapy." (PMID 40839565, 2025). "CXCL8, also known as IL-8, promotes angiogenesis during wound healing, tissue repair, and cancer progression." (PMID 40260916, 2025). "Correspondingly, 5 × 2 Gy increased secretion of module 1 (CCL5) and module 4 (CXCL8) chemokines by cancer cells." (PMID 40811032, 2025). "A variety of studies have demonstrated that CXCL8 shows up not only in cancer cells but also in the cells lining blood vessels and in macrophages connected to tumors, including in CRC." (PMID 40943634, 2025). "For example, CXCL8 exhibits high expression levels in mCAF1, and it is widely recognized as a crucial gene promoting angiogenesis, potentially facilitating cancer progression and metastasis." (PMID 39741182, 2025). "Cancer cells after immortalized PDT significantly upregulated a number of immune-related genes, including chemokine genes (CXCL2, CXCL3, IL8/CXCL8) as well as genes encoding interleukin-6 (IL-6) and its receptor (IL6R)." (PMID 38397977, 2024). "CXCL8/IL8 is a well-studied chemokine in multiple cancer types, including colorectal, esophageal, bladder, gastric, breast, and others." (PMID 38385965, 2024). "A paracrine loop between cancer cells and TAMs, whereby TAM derived IL-6 activates STAT3/GLUT3 pathway in cancer cells to preserve high CXCL8 levels was suggested." (PMID 39044824, 2024). "In the same type of cancer, CXCL8 mediates the intensification of aerobic glycolysis and restricts the production of reactive oxygen species (ROS), which subsequently translates to enhanced cell proliferation and invasion." (PMID 39595551, 2024). "Since mice do not have a homolog of the IL-8/CXCL8 gene, which is present in other species, including humans, compared to other cytokines, our understanding of the mechanisms that regulate IL-8 expression in cancer cells has been lagging." (PMID 39123403, 2024). "CXCL8 expression on cancer cells can be induced by inflammatory cytokines such as TNFα and IL1β, as well as by stress conditions including hypoxia, oxidative stress, and exposure to chemical agents." (PMID 39409924, 2024). "Overexpression of CXCL Genes: Several CXCL genes (e.g. CXCL1, CXCL3, CXCL8) show significant overexpression, indicating their potential role in promoting tumorigenesis and cancer progression." (PMID 39546375, 2024). "Chemokines such as CXCL8 (IL-8) promote cancer cell migration, invasion, and angiogenesis by interacting with their receptors on endothelial cells." (PMID 39200315, 2024). "A positive correlation was discovered between MnSOD expression, CXCL8 levels, and neutrophil infiltration, indicating the involvement of the “MnSOD-CXCL8-neutrophil recruitment” pathway in cancer advancement." (PMID 38999951, 2024). "The role of CXCL1 in tumorigenesis in this cancer is low compared to the significance played by CXCL8/IL-8." (PMID 38673949, 2024). "We were particularly interested in the interactions between the CXCL8 subgroup of cancer cells and endothelial cells, where we demonstrated the further analysis of ligand–receptor interactions for these cells." (PMID 39001509, 2024). "BC cell derived GLUT3 triggers lactate-mediated CXCL8 secretion by cancer cells leading to TAM M1 polarization and expression of IL-1β, TNF-α and IL-6." (PMID 39044824, 2024).
cancer (continued). "Lastly, CXCR2 expression by DCs induces their migration into the tumor through the CXCL8-CXCR2 axis, since CXCL8, a CXCR2 ligand, is expressed by endothelial cells, tumor-associated macrophages (TAMs), and cancer cells." (PMID 39114657, 2024). "Pseudotime analysis implicates IL1β/CXCL8/CXCR2 axis in the progression of neutrophils from health to cancer and metastasis, with effects on T-cell effector function." (PMID 38358352, 2024). "Studies have shown that the interaction between HCC cells and macrophages can facilitate the proliferation and metastasis of cancer cells through the up-regulation of CXCL8/Mir-17 clusters." (PMID 37400985, 2023). "The expression of both chemokines is upregulated by neurotensin (NTS) through ERK MAPK activation, with it being CXCL8 that acts in an autocrine manner on cancer stem cells, increasing their proliferation." (PMID 37408240, 2023). "Cancer cells have been shown to secrete CXCL8 to maintain the aggressive phenotype and inhibit apoptosis." (PMID 36838253, 2023). "Apoptosis of cancer cells can be promoted by inhibiting the expression of CXCL8, while apoptosis can be blocked by activating the JAK-STAT pathway." (PMID 37215082, 2023). "To explore the specific macrophages with CXCL8 expression, we reviewed another recent single-cell RNA-seq dataset focusing on pan-cancer immune cells and fibroblasts." (PMID 37765018, 2023). "The authors found only monocyte and granulocyte DEGs enriched in the cancer pathway, with CXCL8 being the common DEG between GDM and control groups." (PMID 37928902, 2023). "Activation of the JAK-STAT signaling pathway inhibits the proliferation of cancer cells, whereas silent expression of CXCL8 promotes the proliferation of cancer cells." (PMID 37215082, 2023). "CXCL1 (GRO-α) and CXCL8 (IL-8) promote cancer cell survival by inhibiting apoptosis and consequently inducing upregulation of Mdm2 and downregulation of Bcl-2 expression." (PMID 37762405, 2023). "All this suggests that CXCL8 can be used as a cancer biomarker for prognosis and prediction to identify a more aggressive phenotype." (PMID 37640804, 2023). "Chemokines, such as CCL28, CXCL8, and CXCL16, and chemokine receptors, including CCR1, CCR8, and CXCR2, were positively linked to DLAT expression in various cancers." (PMID 37199628, 2023). "Lactate-induced angiogenic neovascularization in cancer cells through the activation of NF-kB/IL-8 (CXCL8) signaling in endothelial cells." (PMID 36984785, 2023). "Cancer-associated endothelial cells (CAEC), under the influence of the accumulated lactate in TME, which results in enhanced IL-8/CXCL-8 signals, can support angiogenesis." (PMID 37328876, 2023). "In established carcinomas, CALB1-negative cancer cells became the dominant source of CXCL8, correlating with neutrophil infiltration and worse prognosis." (PMID 37192000, 2023). "RNA-sequencing analysis revealed that SAT is associated with angiogenesis and neutrophil recruitment, with the activation of TGF-β signaling in LADC cells induced by interaction with CAFs resulting in upregulation of CXCL8 expression in the cancer cells." (PMID 37174001, 2023). "In fact, CXCL8 is so pro-tumorigenic that it has been proposed as a prognostic marker in cancer patients." (PMID 36838253, 2023). "Under the action of exogenous chemotherapeutic drugs, excessive CXCL8 can inhibit the apoptosis of ovarian and gastric cells induced by chemotherapeutic drugs and improve the drug resistance of cancer cells." (PMID 37377954, 2023). "THz demethylation downregulates FOS, JUN, and CXCL8 genes, which are involved in cancer and apoptosis pathways." (PMID 36967404, 2023). "In contrast, stattic down-regulated the ability of TME Stimulation to potentiate the expression of PD-L1 and the release of CXCL8 by the cancer cells (respectively)." (PMID 37190183, 2023).
cancer (continued). "This revealed peaks for TEAD1 and TEAD4 on both KISS1 and CXCL8 promotors, suggesting that within cancer cells, TEAD transcription factors facilitate the expression of genes both up‐ and down‐regulated on NF2 loss." (PMID 36740402, 2023). "A further interesting anti cancer effect of metformin was the ability to reduce the TNF-α-induced CXCL8 secretion by thyroid cells in vitro." (PMID 38146457, 2023). "Expression of CXCL8 is significantly higher in numerous types of cancers, and many studies have evidenced that serum level of CXCL8 in patients with cancer can act as a prognostic marker." (PMID 35372515, 2022). "IL-8 (also known as CXCL8) is mainly produced by macrophages and plays a controversial role in regulating cancer progression." (PMID 36071472, 2022). "As cancer therapy advances, some emerging clinical trials are ongoing to explore the efficacy and safety of combining anti-CXCL8 and ICIs therapy." (PMID 35372515, 2022). "CXCL8/IL-8 is a well-known chemokine that mediates cancer cell motility, invasion and metastasis by promoting epithelial-mesenchymal transition (EMT) while its role in HCC has been little explored." (PMID 35902905, 2022). "Of note, the authors observed that galectin-9 also induced CXCL8 (IL-8) secretion by the cancer cells." (PMID 36497271, 2022). "We found that cotransfection with siPTEN and siOTUD1 attenuated the increase in phosphorylated AKT, VCAM1 and CXCL8 and cancer cell proliferation induced by knockdown of OTUD1 alone." (PMID 35280681, 2022). "Components of TME play a vital role in progression and metastasis of cancer and can induce an upregulated cytokines and chemokines, such as CXCL8." (PMID 35372515, 2022). "As model proteins relevant to chronic inflammation and cancer, we used gas plasma-treated insulin and CXCL8." (PMID 36366323, 2022). "Upon cancer cells and some types of stroma cells secreting CXCL8 in TME, endothelial cells begin to express and secret matrix metalloproteinases (MMPs) to break down the extracellular matrix (ECM), then, resulting in angiogenesis." (PMID 35372515, 2022). "GEPIA database was used to explore the relationship with mRNA expression of CXCL8/9/10/11/13 and cancer stage of patients with HNC." (PMID 35905218, 2022). "Many excellent reviews demonstrate the role of CXCL8-CXCR1/2 axis in target therapy, chemotherapy and the prognostic role of plasma level of CXCL8 in cancer." (PMID 35372515, 2022). "Clinical trials (NCT00798655, NCT04810585, NCT02329639) are examining the potential of CXCL8 as a biomarker for therapy response and prognosis in a panel of different cancers; which would hopefully include EOC in the near future." (PMID 35269786, 2022). "Several chemokines enriched in chemotaxis terms, including CXCL8/11/1/10/5, were significantly increased in cancer tissues." (PMID 35909892, 2022). "The importance of the CCL2/CCR2 and CXCL8/CXCR2 axes in various cancers has led to the development of several small-molecule inhibitors that target the two axes." (PMID 36403057, 2022). "In the cancer setting, CXCL8 plays important roles in neutrophil chemotaxis, facilitating angiogenesis, invasion, and metastasis." (PMID 35879507, 2022). "A total of 73 genes with pearson correlation coefficient (PCC) ≥ 0.30 were found, in which cancer-associated chemokines CCL20, CXCL8 and CXCL3 were extremely associated with CXCL1 expression." (PMID 35764974, 2022). "Our findings revealed an important role of DCLK1, a marker of some cancer stem cells, in mediating thrombin-stimulated IL-8/CXCL8 expression in human lung epithelial cells." (PMID 36369000, 2022). "The high expression level of CXCL8 in ESCC cancer cells is closely related to the poor prognosis of lymph node metastasis." (PMID 36295640, 2022). "M2-like TAM infiltration in TME also observed to increase the expression of CXCL8, which promoted the cancer progression by affecting migration and invasion processes of bladder cells." (PMID 39280890, 2022).